ARG1 (arginase 1)
Diseases named in the same sentence as ARG1 in open-access papers (continued):
Sharing a sentence is not in itself a finding about the gene and the disease.
Sepsis (continued). "The results of our study indicate that upregulated IL1R2 and ARG1 may be further correlated with the key role of inflammasome in sepsis." (PMID 31817302, 2019). "While AAMs are generally linked to a higher susceptibility to bacterial infections and inhibit classical macrophage inflammation via arginase 1 production, they may have beneficial effects by lessening sepsis induced tissue damage." (PMID 25611587, 2015). "Four diagnostic genes (APRT, ARG1, UMPS and LDHB) with excellent diagnostic value were identified, which might be mainly concentrated in energy metabolism-related functions and the immune-related pathway in the Sepsis process." (PMID 40774030, 2025). "Notably, the analysis identified potential mediators of sepsis-induced immunosuppression, including Arg-1, SOCS-1, and SOCS-3, which were highly upregulated in multiple cell types and negative costimulatory molecules, including PD-1 and CTLA-4 upregulated in sepsis." (PMID 37317092, 2023). "Besides, ROC curves generated from these datasets further confirmed the role of ARG1 in sepsis." (PMID 35739592, 2022). "ARG1 was the only overlapped gene in both results and could be used to make an accurate diagnosis, discriminate the severity and predict the treatment response of sepsis." (PMID 35739592, 2022). "In addition, Shionone may reduce inflammatory factor levels through the promotion of M2 macrophages by GM-CSF/STAT5/Arg1 pathway to alleviate sepsis induced inflammation in vitro." (PMID 35141243, 2021). "As an important hub gene between SAP and sepsis, ARG1 (Arginase 1) is a member of the urea hydrolase family and participates in the metabolism of arginine by catalyzing the hydrolysis of arginine into urea and ornithine." (PMID 39364223, 2024). "ARG1 and HP, identified as crucial hub genes between SAP and sepsis, play a vital role in the immunological response." (PMID 39364223, 2024). "Our research indicates that both ARG1 and HP were upregulated in SAP and sepsis and showed good predictive properties with an AUC ≥0.800 in both test and validation sets." (PMID 39364223, 2024). "Conversely, the difference in expression levels between ARG1 and CCR7 was consistently higher in sepsis samples compared to normal samples." (PMID 39710434, 2024). "We found that ARG1 and HP are the most important hub genes between SAP and sepsis, and the NLR signaling pathway is a common regulatory pathway for these two diseases." (PMID 39364223, 2024). "Three machine learning results revealed that two overlapping genes (ARG1, HP) were identified as shared hub genes for SAP and sepsis." (PMID 39364223, 2024). "Our diagnostic nomogram incorporates critical insights into the NLR signaling pathway, particularly through the hub genes ARG1 and HP, which bridge SAP and sepsis." (PMID 39364223, 2024). "The CoIP results confirmed direct interactions between MMP8, MMP9, ARG1, and CXCL8, substantiating their roles in sepsis-related inflammatory pathways." (PMID 39560539, 2024). "Providing external validation to our findings, several genes, such as CD177, ARG1 (arginase), MMP9, OLAH and ADM have been described previously as having important inflammatory roles in sepsis." (PMID 38332914, 2023). "In contrast, M2-type macrophages produce high levels of Arg-1, CD206, IL-10, and transforming growth factor beta (TGF-β), which play an immunomodulatory role and have a therapeutic effect on sepsis." (PMID 38066526, 2023). "An immune cell-specific study has found that MMP9, ARG1, CXCL3, SOCS3, CCR7, and IL-10 are differentially expressed in T cells and monocytes from sepsis patients compared with healthy individuals." (PMID 35721566, 2022). "The DEGs (IL1R2, ARG1, FCGR1A, MMP9, ELANE, and MPO) that were common on day1 and day3 of sepsis, with at least 2.0-fold upregulation, were selected for constructing and visualizing the PPI network using Cytoscape." (PMID 31817302, 2019).
Sepsis (continued). "Using a meta-analysis and network-based approach on samples of sepsis and normal healthy controls, we identified the key genes for inflammation in sepsis with increased expression of IL1R2 and ARG1, as indicated by semiquantitative-PCR studies." (PMID 31817302, 2019). "APRT, ARG1, UMPS, and LDHB might be new ideas for studies related to the diagnosis and treatment of Sepsis." (PMID 40774030, 2025). "ARG1 and HP may affect SAP and sepsis by regulating inflammation and immune responses, shedding light on potential future diagnostic and therapeutic approaches for SAP-associated sepsis." (PMID 39364223, 2024). "S1PR5, GNLY, CD247, KLRG1, IL-1R2, AUTS2, IL-2Rβ, ARG1, TGFBR3, TLR5 and PRF1 in the top 80 genes in the two modules were located toward the center of the co-expression network, and CD247, IL-2Rβ, TGF-βR3 and IL-1R2 were identified as core genes in sepsis." (PMID 36855106, 2023). "CD177, ARG1, FAM20A, PCOLCE2, SLC51A, MMP9, were identified as most significantly upregulated in both SIRS and Sepsis on Day1, compared with healthy controls, with CD177 and ARG1 consistently higher for both SIRS and Sepsis at this and across all timepoints to discharge." (PMID 38332914, 2023). "However, Arg1 expression by CD4+ and CD8+ T cells has been described in patients with sepsis, indicating a potential role for generic infectious stimuli and/or an antigen-driven process mediated via the TCR." (PMID 37440306, 2023). "Since septic shock is a severe form of sepsis, and shares similar signs and symptoms with non-septic shock, it is of great value to utilize ARG1 as a potential biomarker to distinguish the two conditions in clinical practice." (PMID 35739592, 2022). "Another interesting finding in this study is that heart tissue from rSj-Cys-treated sepsis-mice expressed more Arg-1 and less iNOS compared to the mice without rSj-Cys treatment." (PMID 32423469, 2020). "In particular, Uhel and colleagues found that G-MDSCs were specifically increased in sepsis patients, compared to other ICU patients, and that high levels of G-MDSCs and arginase 1 early after the onset of infection were predictors for subsequent nosocomial infections." (PMID 31075836, 2019). "However, FIZZ1 and Arg-1 mRNA expression remained low in all three groups, indicating that HBP promoted M1 differentiation following sepsis-induced AKI." (PMID 29723248, 2018). "Our results in the S. aureus sepsis model, demonstrated that TNF-α signaling through TNFR1 is not required for MDSC expansion and accumulation but it is critical for the expression of MDSC immunosuppressive mediators such as Arginase 1 and iNOS." (PMID 30123776, 2018). "There was also a strong correlation between renal tissue iron overload with iNOS upregulation iNOs/Arg1 ratio, CD8+, CD68+, and CD163+ macrophage phenotype, indicating the impacts of both iron overload and inflammatory macrophages on each other within 72 h of induction of sepsis." (PMID 39949667, 2025). "Finally, the expression of the topmost upregulated genes (ARG1, IL1R2, ELANE, MMP9) was quantified by reverse transcriptase-PCR (RT-PCR), and myeloperoxidase (MPO) expression was confirmed by immunohistochemistry (IHC) staining in the lungs of a well-established sepsis mouse model." (PMID 31817302, 2019). "Top ranked hits included FAM20A, PPARG, ADM and ARG1, many of which are commonly expressed in both SIRS and sepsis disease groups relative to controls and are non-specific." (PMID 38332914, 2023). "Real-time PCR analysis showed increased iNOS expression in the kidneys of the four groups of mice but no increase in Arg-1 or FIZZ1 expression, suggesting that HBP activated M1 macrophages in sepsis-induced AKI." (PMID 29723248, 2018).
lung carcinoma (53 papers, 2011 to 2026). "The effects of Arg-1 inhibition on BCG pleurisy-associated lung cancer cells were evaluated in vivo." (PMID 38720340, 2024). "We evaluated the treatment efficacy of inhibiting Arg-1 M2 MФ polarization in TB-associated lung cancer in vitro and in vivo using a Mycobacterium bovis bacillus Calmette–Guérin (BCG)-induced pleurisy mouse model." (PMID 38720340, 2024). "Our results showed the translational potential of Arg-1 inhibitors for TB-associated lung cancer and demonstrated a challenge for the metabolic regulation of immune responses in both TB and lung cancer." (PMID 38720340, 2024). "We found that the Arg-1 inhibitor suppressed cancer progression by modulating autophagy and E-cadherin signaling in TB-associated lung cancer." (PMID 38720340, 2024). "We found that Arg-1 MФ play an important role in the progression of lung cancer in TB-associated microenvironments." (PMID 38720340, 2024). "Lastly, elevated expression of IL-9R and Arg1 in tumor lesions is associated with poor prognosis in lung cancer patients." (PMID 35778404, 2022). "Enhanced expression of Arg-1 associated with TAMs was found in 3LL murine lung carcinoma, in the human papillomavirus E6/E7-expressing murine tumors and in CD11b+/CD14− myeloid cells from renal carcinoma patients." (PMID 21901144, 2011). "Therefore, M2 Arg-1+ tumor associated MФ may be a novel therapeutic target for tuberculous fibrosis-induced lung cancer progression." (PMID 38720340, 2024). "Moreover, high Arg1 gene expression is associated with poor survival in human lung cancer patients." (PMID 27602772, 2016). "In human lung, ARG1 has been found to be expressed in neutrophils, based on data from lung cancer specimens." (PMID 40875483, 2025). "By activating TLR2 signaling and secreting inhibitory molecules such as arginase 1 and eSIRT2, it promotes malignant growth of lung cancer." (PMID 40727252, 2025). "Arg-1 M2 polarization–autophagy/E-cadherin signaling is involved in TB-related lung cancer progression." (PMID 38720340, 2024). "Tuberculous pleural fibrosis induces M2 Arg-1+ polarization, and M2 Arg-1+ MФ contribute to lung cancer metastasis via autophagy and E-cadherin signaling." (PMID 38720340, 2024). "An inhibitor of arginase-1 targeting M2 Arg-1+ MФ both in vitro and in vivo significantly reduced tuberculous fibrosis-induced metastatic potential of lung cancer and decreased autophagy signaling and E-cadherin expression." (PMID 38720340, 2024). "TPE-induced M2 Arg-1+ MФ polarization facilitated lung cancer proliferation via autophagy signaling and E-cadherin signaling in vitro." (PMID 38720340, 2024). "Most importantly, we found that Arg-1+ MФ polarization induced by TPE contributed to lung cancer proliferation by enhancing autophagy signaling and E-cadherin expression." (PMID 38720340, 2024). "Of note, TAMs (IMs) were the major population of Arg1 producers in both this model and lung cancer patients." (PMID 35778404, 2022). "In those with renal or lung carcinoma, either depletion of MDSCs or inhibition of Arg-1 was found to reestablish T-cell proliferation and TCR CD3 ζ-chain expression." (PMID 35092727, 2022). "Initially, we utilized flow cytometry to determine which neutrophil subsets harbored ARG1 protein in the context of lung cancer." (PMID 36377658, 2022). "Systemic or bone marrow-specific ARG1 deletions can improve antigen-induced proliferation of adoptive transferred T cells and lead to inhibition of lung cancer tumor growth." (PMID 35190747, 2022). "Consistent with our results in mouse models, high expression of ARG1 and IL6 associated with poor survival probability in lung cancer patients." (PMID 35778404, 2022). "We utilized 2 mouse models of lung cancer to investigate the ARG1 profile in neutrophil lineage cells: the Lkb1fl/fl; Ptenfl/fl (PL) model of LUSQ and the Lewis lung carcinoma (LLC) allograft model of LUAD." (PMID 36377658, 2022).
lung carcinoma (continued). "Immune-suppressive factors, TGF-β and Arg-1, were also up-regulated in lung cancer at the same time." (PMID 33814009, 2021). "In 3LL murine lung carcinoma, Gr-1−CD11b+ myeloid suppressor cells expressed increased levels of intra-cytosolic arginase-1 and the cationic amino acid transporter 2B, which imports extracellular L-arginine." (PMID 34203451, 2021). "TAMs in lung cancer and melanoma also express more ARG1 than all other cells within tumor combined and have over 20 times higher expression of ARG1 as compared with peritoneal macrophages." (PMID 32499785, 2020). "It was found that prostanoids produced by COX2 are responsible for mediating ARG1 overexpression in MDSCs by lung cancer cells in in vitro and in vivo models." (PMID 32499785, 2020). "According to the correlation analysis, RUNXOR expression was positively correlated with the proportion of MDSCs and Arg1 level, which is the main suppressive molecule of MDSCs, in the peripheral blood of lung cancer patients." (PMID 29914443, 2018). "Correlation analysis showed that HOXA1 levels were negatively correlated with the proportion of MDSCs and the Arg1 levels in the peripheral blood of patients with lung cancer." (PMID 29662483, 2018). "Myeloid cells expressing elevated Arg1 from a lung carcinoma model blunt T cell function vial-arginine sequestration and facilitate tumor escape, and CD8+ T cells supplemented with l-arginine mount greater anti-tumor responses than untreated controls." (PMID 29201027, 2017). "PM2.5-pretreated BMDMs exhibited an immunosuppressive programmed cell death ligand 1 (PD-L1)+/arginase 1 (Arg1)+ phenotype, and their conditioned media significantly promoted proliferation, migration, and colony formation of Lewis lung carcinoma cells (LLC) and B16 melanoma cells (B16) (P<0.05)." (PMID 41309249, 2025). "The alkaloid SNG similar reduces both Arg1 and iNOS expression in MDSCs allowing enhanced anti-tumour activity against murine lung cancer, and MDSC accumulation in lung cancer was found to be iNOS-dependent as shown using iNOS knockout mouse models where tumour MDSC numbers were impaired." (PMID 38464388, 2024). "Consequently, PPARγ activation in macrophages has been shown to fuel lung cancer progression and metastasis, especially through increased arginase 1 and TGFβ1 expression." (PMID 35954274, 2022). "Since we have shown IL-9 promotes tumor growth by upregulation of Arg1 expression in mouse models, we next wanted to investigate whether this paradigm was conserved in the development of human lung cancer." (PMID 35778404, 2022). "Thus, our study suggests the IL-9/macrophage/Arg1 axis is a potential therapeutic target for lung cancer therapy." (PMID 35778404, 2022). "TRAF6 and arginase 1 were highly expressed in MDSCs of patients with lung cancer." (PMID 33717204, 2021). "In addition, the expression of TRAF6 was increased in MDSCs from lung cancer patients, which was positively correlated with the level of Arg1 in MDSCs." (PMID 33717204, 2021). "By using the expression pattern of signature genes identifying the N1 state (Tnf, Fas), the N2 state (Arg1, Ccl2), and immature neutrophils (Stmn1, Ube2c), pseudotime analysis confirmed the developmental direction of TANs with N2 as an early state of TANs in the lung cancer TME." (PMID 37002229, 2023). "In addition, we also found that high-intensity intermittent exercise down-regulated the mRNA level of Arg-1 in the spleen tissue of lung cancer mice, and tended to decrease the level of CD206 mRNA, but it did not increase the expression of macrophage M1-type markers." (PMID 36186906, 2022). "PPARγ agonist activation in orthotopic and spontaneous murine lung cancer models significantly increased metastasis formation through its upregulated expression in macrophages, which contributed to tumor progression and metastasis through increased arginase 1 expression." (PMID 35954274, 2022).
lung carcinoma (continued). "Furthermore, we isolated F4/80+ TAMs from PBS- or HCQ-treated mice with orthotopic lung cancer, and we found that the M1-like molecules (Nos2, Ifng, IL12b,and IL1b) were up-regulated and the M2-like molecules (Arg1, Tgfb1, IL10, and Ido1) were down-regulated with HCQ treatment." (PMID 30373678, 2018). "Matrine, a naturally occurring alkaloid found in Sophora flavescens, reduces IL-10, Arg-1, and CD206 in TAMs in lung cancer models." (PMID 40723226, 2025). "In summary, we demonstrated that TPE induces Arg-1 M2 polarization of MФ via CXCL9/CXCL10, which promotes the progression of lung cancer via autophagy/E-cadherin signaling." (PMID 38720340, 2024). "MDSCs within prostate or lung cancer have higher expression levels of ARG1, ARG2, NOS2, NOS3, and S100A9 than splenic MDSCs, with ARG1 being the highest." (PMID 38720342, 2024). "Genetic ablation of Arg1 in macrophages or blocking ARG1 in vivo can restrain tumor growth and boost the anti-tumor efficacy of adoptive cell transfer (ACT) therapy in EG7 lymphoma and 3LL lung carcinoma in mice." (PMID 34988072, 2021). "COX-2 induction was responsible for the arginase-1 upregulation in Gr-1− CD11b+ myeloid suppressor cells, and blocking COX-2 in vivo decreased the tumor volume in a mouse model of lung carcinoma." (PMID 34203451, 2021). "Qing-Re-Huo-Xue (QRHX) formulae increases the expression of iNOS and decreases the expression of IL-6, TNF-α, and Arg-1 through the JAK2/STAT3 pathway, further reducing the numbers of TAMs and inhibiting tumor growth in lung cancer mouse model." (PMID 33748122, 2021). "Similar to HOTAIRM1, HOXA1 expression levels were negatively correlated with the proportion of MDSCs and Arg1 levels and positively correlated with the number of Th1/CTL cells in the peripheral blood of patients with lung cancer." (PMID 29662483, 2018). "In lung cancer models, the chemokine monocyte chemoattractant protein-1 (CCL2) positively correlates with MDSC frequency, and antibody-mediated blockade of CCL2 reduces both G-MDSCs and M-MDSCs in tumours reducing iNOS and Arg1 expression." (PMID 38464388, 2024). "Furthermore, flow cytometry showed that percentage of Arg1+ cells were markedly reduced in LLC tumor derived-MDSCs and urethane-induced lung cancer tissues of Ffar2−/− mice." (PMID 38402237, 2024). "Here, we showed that neutrophil lineage cells and not monocytes or macrophages expressed ARG1 in human non–small cell lung cancer (NSCLC)." (PMID 36377658, 2022). "Interestingly, the increased expression of RUNXOR has been reported in the PBMCs of patients with lung cancer, and a positive correlation has been described between RUNXOR expression and the presence of MDSCs, as well as Arg-1 production in such patients." (PMID 31404149, 2019). "However, in lung cancer, CD11c+ TAMs may exhibit pro-tumorigenic effects when influenced by CD4+ T cells via interleukin-9 (IL-9)/arginase 1 (Arg1) axis." (PMID 41341850, 2025). "(ii) The conserved upregulation of TAM-promoting genes (e.g., Arg1, Mrc1 and F13a1) across tumour types suggests that SFV-based therapies could have broader applicability in reprogramming TAMs in other malignancies, such as glioblastoma or lung cancer." (PMID 40547518, 2025). "Increased numbers of MDSCs in patients with lung cancer may inhibit the generation of protective immune CD8+ T cells, and the highly expressed iNOS and L-arginase I (Arg-1) of MDSCs promote the downregulation of CD3ζ chain expression of CD8+ T cells and inhibit the immune function of CD8+ T cells." (PMID 37857728, 2023). "The RUNXOR level was positively correlated with the MDSCs percentage and Arg1 level, while it was negatively correlated with the proportion of Th1/CTL cells, which indicated that RUNXOR expression may be involved in the immunosuppression of MDSCs in lung cancer patients." (PMID 29914443, 2018).
lung carcinoma (continued). "Furthermore, only the expression of PPAR-γ and Arg1 but not other key transcription factors such as STAT1, STAT3 and C/EBPβ was dramatically reduced in Ffar2−/− MDSCs and urethane-induced lung cancer tissues." (PMID 38402237, 2024).